RNU6-1159P (RNA, U6 small nuclear 1159, pseudogene)
Gene: Small nuclear RNA gene on chromosome 20 (15,021,553 to 15,021,659, reverse strand). Ensembl gene ENSG00000199803.
Homologues: Orthologues: chimpanzee U6 (97% identical), macaque U6 (96% identical), dog U6 (76% identical), rat LOC120095710 (75% identical). Paralogues in human: RNU6-115P (94% identical), RNU6-797P (90% identical), RNU6-1152P (87% identical), RNU6-1243P (87% identical), RNU6-1209P (86% identical), RNU6-16P (86% identical), RNU6-183P (86% identical), RNU6-393P (86% identical), RNU6-41P (86% identical), RNU6-1008P (85% identical), RNU6-1047P (85% identical), RNU6-1083P (85% identical), and 1283 more.